CCR4 (C-C motif chemokine receptor 4)
Diseases named in the same sentence as CCR4 in open-access papers (continued):
Sharing a sentence is not in itself a finding about the gene and the disease.
mycosis fungoides (23 papers, 2012 to 2026). Classical mycosis fungoides is the most common type of mycosis fungoides (MF), a form of cutaneous T-cell lymphoma, and is characterized by slow progression from patches to more infiltrated plaques and eventually to tumors. "It is a humanized monoclonal antibody that targets CCR4 for the treatment of adult patients with relapsed or refractory mycosis fungoides (MF) or Sézary syndrome (SS)." (PMID 39584990, 2024). "We observed a disproportionately severe and fatal presentation of aspergillosis in a patient affected by mycosis fungoides, receiving treatment with the CCR-4 antagonist Mogamulizumab." (PMID 39194909, 2024). "CCR4 is consistently overexpressed in mycosis fungoides and Sézary syndrome, and a high number of CCR4-positive T cells has been associated with poor prognosis." (PMID 36765704, 2023). "Mogamulizumab, a humanized anti-CCR4 antibody, was approved for mycosis fungoides (MF) and Sézary syndrome (SS), which are a malignancy of skin-homing malignant T cells." (PMID 33633737, 2020). "Notably, CD163+CD206+ TAMs produce M2 macrophage-related chemokines such as CCL22 by the stimulation of IL-4 in cancer stroma, which leads to recruitment of CCR4+ lymphoma cells to develop tumor formation in mycosis fungoides." (PMID 35409404, 2022). "Three chemokine antagonists have been approved: Maraviroc (a CCR5 antagonist) for anti-HIV treatment, Plerixafor (a CXCR4 antagonist) for the treatment of multiple myeloma or non-Hodgkin’s lymphoma, and Mogamulizumab (a CCR4 antagonist) for the treatment of mycosis fungoides or Sézary syndrome." (PMID 34017692, 2021). "For example, the monoclonal antibody against CCR4, mogamulizumab, is approved for relapsed or refractory mycosis fungoides (MF) or Sézary syndrome (SS)." (PMID 38318526, 2024). "Mogamulizumab (Poteligeo®), developed as anti-CCR4 (CC chemokine receptor 4) mAb using POTELLIGENT® by Kyowa Kirin, was approved for the treatment of relapsed or refractory mycosis fungoides and Sézary disease in 2018 by the FDA." (PMID 35884906, 2022). "Defucosylated anti-C-C chemokine receptor 4 (CCR4) IgG1 has been approved by the US Food and Drug Administration (FDA) for the treatment of relapsed or refractory mycosis fungoides or Sézary syndrome 23,24." (PMID 33859756, 2021). "CCR4 is also expressed on other types of PTCL (29 % of total cases; PTCL-NOS, 38 %; AITL, 35 %; ALK- ALCL, 67 %; mycosis fungoides [MF], 41 %)." (PMID 22538464, 2012). "While CCR4 expression is typically confined to regulatory T cells (Treg) and type 2 T helper (Th2) cells in normal environments, this membranous receptor is found to be overexpressed in certain T-cell malignancies, notably in advanced stages of mycosis fungoides (MF) and Sezary syndrome (SS)." (PMID 38396877, 2024). "Notably, since CCL17 and CCL22 are ligands of CCR4, the major chemokine receptor expressed in CTCL cells, the production of these chemokines from TAMs could result in tumor formation in mycosis fungoides in the tumor stage." (PMID 35409404, 2022).
allergic disease (20 papers, 2012 to 2025). An immune response that occurs following re-exposure to an innocuous antigen, and that requires the presence of existing antibodies against that antigen. "Similar to the allergy model, CCR4 inhibition resulted in a reduction of Th2/Th17-associated cytokines, while the levels of IL-10 were increased." (PMID 33669094, 2021). "The strong expression of CCR4 on skin-homing T cells expressing cutaneous lymphocyte antigen and on T cells polarized towards the Th2 phenotype is suggestive of CCR4 involvement in skin-associated immune responses and allergies." (PMID 29099057, 2017). "In this report, we extended our investigation to allergy model induced by A. fumigatus and showed that CCR4 antagonists render protection by targeting Th2 cells." (PMID 33669094, 2021). "The predominant expression of CCR4 in Th2 cells, as well as the upregulation of CCL17 and CCL22 in allergic diseases, have captured attention for their potential therapeutic targeting of CCR4 in the treatment of allergies." (PMID 33669094, 2021). "Several small-molecule CCR4 antagonists have been shown to have efficacy in allergy and tumor growth disease models, and have thus been advanced to a clinical study stage." (PMID 29099057, 2017). "The importance of the CCR4 axis in allergic diseases has been demonstrated in mouse models of atopic dermatitis and asthma." (PMID 27376063, 2016). "CCR4 is expressed by regulatory T cells, mast cells and Th2 cells and is known to play a pivotal role in allergic diseases." (PMID 26003185, 2016). "Collectively, these data strongly suggest that CCR3 and CCR4 are important therapeutic targets for a variety of allergic diseases." (PMID 27376063, 2016). "Therefore, in the present manuscript, we have extended the potential clinical application of CCR4 antagonism in different pre-clinical models of Aspergillus infection and allergy." (PMID 33669094, 2021). "Whether vaccination with CCR4 antagonists in Aspergillus infection or allergy models also induces CTL responses remain to be determined." (PMID 33669094, 2021). "In contrast, markers of immune maturation, such as the number of CD4+ T cells/mL blood and the proportion of T cells expressing the memory marker CD45RO or the homing receptor CCR4, appeared furthest away from the allergy diagnosis at either 3 or 8 years of age (respectively)." (PMID 33007868, 2020). "We found that CCR4 expression is controlled at multiple levels, suggestive of an important role for this receptor in tissue homeostasis and the control of Th2 inflammation, underscoring the potential for CCR4 targeting in the treatment of allergic disease." (PMID 32052476, 2020). "According to these studies, targeting the interactions between CCL17/CCL22 and CCR4 may be a useful approach for controlling allergic diseases." (PMID 30718772, 2019). "Therefore, CCR3 and CCR4 have long been highlighted as potent therapeutic targets for allergic diseases." (PMID 27376063, 2016). "On the other hand, CCR4 mediates allergy-promoting Th2 cell recruitment." (PMID 27829417, 2016). "Indeed, CCR4+ T cells have been shown to be elevated at the sites of inflammation in a number of allergic diseases and numbers are further increased after allergen challenge." (PMID 25505571, 2013). "Thus, CCR3 and CCR4 have been paid attention as potent therapeutic targets for allergic diseases." (PMID 27376063, 2016). "It is well known that the CCR4 and its ligands CCL17 and CCL22 played an important role in allergic diseases." (PMID 29118379, 2017). "As TH2 cells selectively express CCR3, CCR4, and CCR8, these data suggest that Ephedra Herb has a potency to strongly suppress cell migration of TH2 cells and TH2 cell-mediated allergic reactions." (PMID 27376063, 2016). "Chemokine receptors CCR3 and CCR4 are preferentially expressed by TH2 cells, mast cells, and/or eosinophils, all of which are involved in the pathogenesis of allergic diseases." (PMID 27376063, 2016).
allergic disease (continued). "In particular, we demonstrated that Ephedra Herb is a potential medical agent for TH2-mediated allergic diseases by inhibiting the cell migration mediated by the TH2-relevant chemokine receptors such as CCR3, CCR4, and CCR8." (PMID 27376063, 2016). "IL‐9 producing TH9 cells (CCR4− CCR6+ CCR10− CXCR3+) can be induced by the growth factor TGF‐β and IL‐4 from TH2 cells and are similarly involved in immunity against intestinal helminths and onset of allergies." (PMID 36740883, 2023). "TH2 cells (CCR4+ CCR6− CCR10− CXCR3−) orchestrate defense against large extracellular pathogens and helminths by secretion of IL‐4, but are also involved in inflammatory disorders, such as asthma and allergies." (PMID 36740883, 2023). "Currently, the source of IFN-γ in CCR4 antagonist-treated mice either in Aspergillus infection or allergy models is not known." (PMID 33669094, 2021). "The ability of CCR4 antagonists to protect against Aspergillus-induced allergic diseases did not come without expectation." (PMID 33669094, 2021). "The expression of CCR4 on TH2 cells has prompted some interest in it as a therapeutic target for asthma and other allergic diseases as the cytokines produced by these cells (interleukins 4, 5, 9, and 13) are thought to induce the pathological changes associated with these diseases." (PMID 25505571, 2013). "Therefore, CCR4 and its three ligands (TARC, MDC, and CKLF1) play important roles in allergic inflammations, and CCR4 antagonists have a huge potential in the therapeutics of the allergic diseases." (PMID 22907157, 2012).
Hodgkins lymphoma (19 papers, 2012 to 2024). A heterogeneous group of malignant lymphoid neoplasms of B-cell origin characterized histologically by the presence of Hodgkin and Reed-Sternberg (HRS) cells in the vast majority of cases. "MYO1G is abundant in T and B lymphocytes and mast cells, and CCR4 is a novel-specific molecular target for immunotherapy in Hodgkin lymphoma, able to regulate the cell trafficking of various leukocyte types." (PMID 35799269, 2022). "We have previously reported that manipulating the TARC/CCR4 chemokine/chemokine receptor pathway enhances CAR-T cell antitumor activity in Hodgkin’s lymphoma models." (PMID 35443752, 2022). "For instance, the co-expression of the chemokine receptor C-C chemokine receptor type 4 (CCR4) with a CAR construct increased the accumulation of cytotoxic T cells in a Hodgkin lymphoma model." (PMID 33287224, 2020). "Further, forced expression of CCR4 by CD30 CAR T cells in a Hodgkin lymphoma model, enhances their homing to Reed-Stemberg cells secreting CCL17 and CCL22, the ligand of CCR4." (PMID 32423475, 2020). "Co-expression of a CAR targeting the CD30 antigen on Hodgkin's lymphoma with CCR4 enhanced antitumour activity in vivo in a xenograft model 2009." (PMID 23198862, 2013). "It has been shown that T cells engineered to express CXCR2 will preferentially traffic to melanomas 102, whereas T cells expressing CCR4 will traffic to Hodgkin's lymphoma 2009." (PMID 23198862, 2013). "The administration of anti-CCR4 antibody effectively depletes CCR4+ T cells and inhibits TReg cells migration in Hodgkin lymphoma." (PMID 22481922, 2012). "Moreover, the activation of CC-chemokine ligand 17 (CCL17) and CCL22, secreted by Reed–Sternberg cells of Hodgkin lymphoma (HL), activated their receptor CC-chemokine receptor 4 (CCR4) expressed T helper cells and Tregs." (PMID 39134804, 2024). "For instance, Hodgkin lymphoma can produce chemokine CCL17 and CCL22 which are attractants for the CCR4-expressing T helper 2 (Th2) and regulatory T (Treg) cells, but not for the CD8+ T cells, which lack CCR4 expression." (PMID 35071966, 2022). "Based on that, researchers have engineered CCR4-expressing CAR T cells, which have shown improved homing and antitumor activity when infused intravenously in mice engrafted with human Hodgkin lymphoma." (PMID 35071966, 2022). "Interestingly, the forced expression of C-C chemokine receptor type 4 (CCR4) could enhance CAR T cell accumulation and therapeutic response in Hodgkin’s lymphoma." (PMID 36721153, 2023).
ovarian carcinoma (19 papers, 2011 to 2025). A malignant neoplasm originating from the surface ovarian epithelium. "Since T cells expressing CCR4 can respond to chemoatractants (CCL22) secreted by ovarian cancer cells, and CCR4+ Treg have been associated with enhanced tumour recurrence, it may be further timely to address the effect of first line treatment on their frequencies." (PMID 24213326, 2012). "Treg cells expressing CCR4 were shown to be attracted to CCL22 released by myeloid cells in ovarian cancer, and the anti-CCR4 mAb Mogamulizumab effectively elicited anticancer responses via the depletion of effector Treg cells in solid tumors." (PMID 36230505, 2022). "For example, Curiel at al. demonstrated that CCL22 secreted by TAMs recruits CCR4+ nTregs to promote the formation of immunosuppressive microenvironment inhuman ovarian cancer." (PMID 31629410, 2019). "Accordingly, the application of an anti-CCR4 antibody in an experimental model of ovarian carcinoma blocked Treg migration and enhanced antitumor response including increased IFNγ secretion by CD8+ T cells." (PMID 28275576, 2017). "For example, a study found that CCR4+ Tregs migrate to the tumor tissue through CCL22 secreted by ovarian cancer cells." (PMID 28388539, 2017). "The ovarian cancer environment caused migration of CTLA4+ FOXP3+ GITR+ Tregs via the chemokine CCL22, secreted by tumor cells and TAMs, and its receptor CCR4, expressed by infiltrating Tregs." (PMID 28275576, 2017). "Studies with human ovarian cancers have shown that Treg-cells traffick to the tumor mass and ascites via chemokine receptor CCR4 responding to CCL22 released by tumor cells and tumor-associated macrophages (TAMs)." (PMID 21559338, 2011). "In this same ovarian cancer model, IL-2 treatment was shown to up-regulate CCR4 as well as CXCR4, which further enhanced the ability of Treg to migrate to the tumor microenvironment based on its elevated levels of the Treg ligands CCL22 and CXCL12." (PMID 22112546, 2011). "Studies with human ovarian cancers have revealed that Treg-cells home to the tumor mass and ascites via CCR4 in response to tumor cell- and TAM-derived CCL22." (PMID 21559338, 2011). "Consequently, targeting CCR4 in clinical trials holds potential to provide a new and reliable strategy for immunotherapeutic intervention in ovarian cancer." (PMID 40703514, 2025). "Anti-CCR4 mAb could be an excellent therapy option for individuals with CCR4+ neoplasms, as well as a novel strategy for treating cancers including HL, B-CLL, ovarian cancer, and EBV-associated disease, in which CCR4+ Tregs prevent the host immune response to the tumor or virus-infected cells." (PMID 35222362, 2022). "In human ovarian carcinoma, CCL22 produced by TAMs mediates trafficking of CCR4+ nTreg cells to the tumor and foster immune privilege." (PMID 31629410, 2019). "Mice inoculated with ovarian cancer cell lines expressing CCL22 accumulate CCR4+ nTreg, which are blocked by administration of anti-CCR4 mAb, further inhibiting tumor size and progression." (PMID 31681327, 2019). "For instance, an anti-CCR4 antibody mAb2-3 blocks Treg migration and stimulates IFNγ secretion by CD8+ T cells, eventually enhancing anticancer response in an experimental model bearing CCL22-secreting ovarian cancer cells." (PMID 28929459, 2018). "Moreover, the ovarian cancer microenvironment can induce migration of CTLA4+ FOXP3+ GITR+ Tregs via the chemokine CCL22 and its receptor CCR4, the latter expressed by infiltrating Tregs." (PMID 28929459, 2018).
glioma (18 papers, 2013 to 2025). A benign or malignant brain and spinal cord tumor that arises from glial cells (astrocytes, oligodendrocytes, ependymal cells). "CC chemokine ligand 2, another chemokine produced by human gliomas and a weaker ligand for CCR4, has also been implicated in glioma-mediated Treg chemotaxis." (PMID 26217588, 2015). "Our group has previously identified C-C motif chemokine 2 (CCL2) as a glioma-derived T-reg chemoattractant acting on chemokine receptor 4 (CCR4) in a murine orthotopic glioma model." (PMID 39046599, 2024). "Our group has previously identified C-C motif chemokine 2 (CCL2) as a glioma-derived T-reg chemoattractant acting on chemokine receptor 4 (CCR4) in a murine orthotopic model of glioma." (PMID 38947002, 2024). "Using murine models, we determined that CCL2 induces Treg recruitment into the glioma microenvironment through the CC chemokine receptor type 4 (CCR4) expressed on Tregs." (PMID 39046599, 2024). "Under these conditions, not only the recruitment of TAMs is inhibited but also the attraction of regulatory T cells via CCR4 and the autocrine mechanism on glioma cells, expressing CCL2 and CCR2, is interrupted." (PMID 32668709, 2020). "Glioma-infiltrating Tregs express particularly high levels of CCR4 compared to other tumor-infiltrating lymphocytes, and several in vitro migration studies have demonstrated the ability of glioma-derived CCL22 to induce Treg chemotaxis." (PMID 26217588, 2015). "Notably, antibody-mediated targeting of the Treg CCL2 high-affinity receptor, CCR4, reduced intertumoral Treg abundance and prolonged survival in a mouse glioma model." (PMID 39046599, 2024). "Our data indicate that targeting either CCL2 or CCR4, alone or in combination, may represent a viable therapeutic strategy to diminish Treg accumulation in the glioma microenvironment." (PMID 39046599, 2024). "The authors also showed that in the absence of CCL2, Tregs failed to accumulate in the GBM TME and that CCR4-deficient mice were defective in glioma accumulation." (PMID 36338705, 2022). "CCL2 recruits immunosuppressive regulatory T cells that express CCR4 to induce Tregs migration to glioma tissue for immune evasion, which is the main sign of tumorigenesis and a powerful obstacle to effective cancer treatment in gliomas." (PMID 36419652, 2022). "It has been reported that microglia cells and macrophages in the glioma microenvironment could secrete chemokine CCL2 to recruit CCR4+ Treg and CCR2+ ly‐6C+ Monocytic MDSCs and suppress tumor immunity." (PMID 34482648, 2021). "Similarly, expression of CCR2 and CCR4 on CAR T cells could increase chemotaxis to CCL2/4/5/17/22-secreting gliomas." (PMID 40895575, 2025). "In gliomas, CCL2's production is vital for recruiting immunosuppressive CCR4+ Tregs and CCR2+ Ly‐6C+ monocytic myeloid‐derived suppressor cells." (PMID 39706820, 2024). "In the tumor microenvironment of human gliomas, CCL2 has been shown to recruit both CCR4+ Treg and CCR2+ Ly6C+ monocytic myeloid-derived suppressive cells." (PMID 38213329, 2023). "GAMs produce CCL2, a chemokine recruiting CCR4+ Treg and CCR2+Ly-6C+ monocytic MDSCs in murine gliomas." (PMID 34504786, 2021). "In vitro administration of blocking antibodies to CCR4 as well as CCL2 receptor, CCR2, arrested Treg migration toward glioma supernatant." (PMID 26217588, 2015). "The CNOT7 (CCR4-NOT Transcription Complex Subunit 7) is an important functional subunit of CCR4-NOT protein complex that has not been reported in glioma." (PMID 38985240, 2025). "In this research, it was the first time to investigate and verify the function of CCR4-NOT protein complex CNOT7 in glioma." (PMID 38985240, 2025). "Importantly, CCL2 then recruits regulatory T cells (Tregs) and myeloid-derived suppressor cells (MDSCs) through CCR4 and CCR2 as significant contributors to the potently immunosuppressive glioma microenvironment." (PMID 32296458, 2020).
glioma (continued). "Gl261 tumors grown in CCL2-deficient mice or mice treated with a small-molecule antagonist of CCL-2 receptor, CCR4, failed to maximally accumulate Tregs and M-MDSCs within the glioma microenvironment." (PMID 32240177, 2020). "For instance, CCL17, another ligand to CCR4, does not appear to play a role in Treg chemotaxis in glioma or ovarian carcinoma but is a key mediator in Hodgkin’s lymphoma and gastric adenocarcinoma." (PMID 26217588, 2015). "In particular, gliomas are known to produce CC chemokine ligand 22 (CCL22), which serves as a potent chemotactic factor for leukocytes expressing CCL22 receptor CC chemokine receptor 4 (CCR4)." (PMID 26217588, 2015). "In glioma, ∼74% of Treg isolated from the peripheral blood of GBM patients express CCR4, which is significantly increased when compared to the ∼43% of Treg expressing CCR4 in healthy (control) patients." (PMID 23720663, 2013). "Overexpression of CCR2, CCR4, CXCR1/2, and CXCR4 reportedly improved CAR T cell trafficking to brain tumors in preclinical studies.CAR T cell pretreatment with metformin/rapamycin also enhanced mitochondrial respiration, leading to improved CAR T cell efficacy in glioma." (PMID 40895575, 2025).